TRPV1 (transient receptor potential cation channel subfamily V member 1)
Diseases named in the same sentence as TRPV1 in open-access papers (continued):
Sharing a sentence is not in itself a finding about the gene and the disease.
cancer (continued). "Since Ki67, VEGFR, and E-cadherin are well-recognized tumor markers for proliferation and metastasis of cancer cells, we further analyzed the association between these tumor markers and TRPV1 expression in GC." (PMID 33008449, 2020). "The scientific data underlines the role of TRPV1 as a potential calcium signaling modulator and drug target against cancer." (PMID 31681615, 2019). "TRPV1 is linked with both the process of inflammation and calcium signaling, thus, its contribution to cancer progression gained more attention." (PMID 31681615, 2019). "Recent studies reported that the tissue damage and inflammation caused by cancer greatly decreases the thresholds of TRPV1 and ASIC3 for sensing noxious stimulation." (PMID 30366393, 2018). "Since then, capsaicin has become the “gold standard” of TRPV1 activation, and has contributed to critical developments over the last 20 years in understanding the role of TRPV1 in pruritis, cancer, weight loss, and in the cannabinoid system." (PMID 29035314, 2017). "A role for TNFR2 receptors in heat hyperalgesia has been implicated in a model of cancer pain where TRPV1 protein up-regulation in DRG neurons is attenuated in TNFR2 knock-out mice." (PMID 20796308, 2010). "In tumor contexts, TRPV1-expressing sensory fibers contribute to cancer-associated pain and may promote tumor progression through neuropeptide release, such as substance P and CGRP." (PMID 41009819, 2025). "The elevated TRPV1 expression is also associated with improved clinical outcomes across various cancers, suggesting that TRPV1 upregulation could be a marker for decreased tumor proliferation and better prognosis." (PMID 39407657, 2024). "TRPV1 expression was recently reported to be closely associated with cancer development." (PMID 38734935, 2024). "In particular, both TRPV1 blockade and knockdown caused a similar synergistic ability, confirming that the TRPV1 blockade plays a crucial role in combating the thermal resistance in cancer thermotherapy." (PMID 37120615, 2023). "In this study, we noted that the cause of TRPV1 overexpression in cisplatin-resistant cancer was due to direct transcriptional regulation by NANOG, but other possibilities may exist." (PMID 37165076, 2023). "Although numerous studies have shown that the expression and activation of TRPV1 have an important role in cancer development, a comprehensive exploration of associations between TRPV1 expression and tumor proliferation, microenvironment, and clinical outcomes in pan-cancer remains insufficient." (PMID 36304985, 2022). "As a result, TRPV1 downregulation was associated with unfavorable clinical outcomes in cancer." (PMID 36304985, 2022). "Greater understanding of the RTx-mediated long-range allostery of TRPV1 could help further the therapeutic potential of RTx, which is a promising drug candidate for pain relief associated with advanced cancer or knee arthritis." (PMID 35610228, 2022). "In this review, we summarize the observations reported to date of the changes in TRPV1 expression and channel activity associated with cancers and the effects of these alterations on cancer cell proliferation, death, and metastasis, and the tumor microenvironment." (PMID 34131404, 2021). "However, the molecular mechanism of action of the TRPV1 antagonists, underlying the anti-cancer activities, remains poorly characterized." (PMID 32604833, 2020). "Similarly, to GBM, TRPV1 expression decreased in invasive BCas with a complete loss of TRPV1 in high-grade cancers." (PMID 31801263, 2019). "TRPV1, meanwhile, has also been linked to the metabolism, longevity, inflammation, and cancer." (PMID 31183372, 2019). "The loss of TRPV1 in high-grade GBM may represent a mechanism by which cancer cells can evade anti-proliferative and pro-apoptotic signals." (PMID 31801263, 2019).
cancer (continued). "The functional expression of TRPV1 splice variants in different cell types e.g., cancer or immune cells has to be addressed in future studies since it might have a great impact on the results." (PMID 31681615, 2019). "Furthermore, in several studies, activation of TRPV1 by capsaicin was associated with anti-cancer effects." (PMID 31681615, 2019). "In the same view, Atf4 induction by prolonged stress exposure triggers apoptosis in cancer cells; so, the enhancement of Atf4 protein expression evidenced in TRPV1 KO thymocytes, may lead to increased susceptibility of thymocytes to apoptotic stimuli." (PMID 29207602, 2017). "Also a low pH in the extracellular milieu activates TRPV1 and is associated with inflammation and the cancer microenvironment." (PMID 28640864, 2017). "All together, these data suggested that TRPV1 could have a role in tumor aggressiveness, since loss of reduction of TRPV1 expression is associated with a more proliferative tumor, as also reported for others cancer cell types." (PMID 27829230, 2016). "Other downstream effectors of TRPV1 related to cellular cancer promoting pathways that may be associated with ERK and Src." (PMID 27200359, 2016). "NGF may also induce the expression of TRPV1 and it is implicated in cancer progression and CIBP." (PMID 39940997, 2025). "In this review, we will describe some possible mechanisms involved in the nociception process associated with cancer that are mediated by factors produced by the TM and which could play an essential role in the direct activation or sensitization of the TRPV1 and TRPA1 channels." (PMID 35053150, 2021). "Notably, it remains controversial whether the TRPV1 antagonist-induced anti-cancer activities are associated with TRPV1 and its calcium signaling." (PMID 32604833, 2020). "Thus, prolonged administration of the p38 MAPK inhibitor may diminish cancer-induced ongoing pain behaviors by multiple mechanisms associated with up-regulation and trafficking of pronociceptive signaling channels (e.g., TRPV1) to the periphery." (PMID 22014040, 2011). "Although, blockade of TRPV1 has been suggested as a possible therapeutic target to relieve pain, recent research has shown that the chronic blockade of this receptor may increase risk of cancer development." (PMID 20422007, 2010). "The expression, prognostic, single-cell value, immune cell infiltration, and immune check-point (ICI) of TRPV1 in pan-cancer were assessed." (PMID 41535811, 2026). "The key point is how to ensure the anti-cancer effect of TRPV1 modulators while overcoming their side effects." (PMID 40007993, 2025). "The changes in TRPV1 expression, the mechanism of change and its role depend on different cancer cell types, which still need further study." (PMID 40007993, 2025). "In the following subsections, we will examine the role of TRPML1, TRPA1, TRPM2 and TRPV1 in cancer processes mediated by oxidative stress in different tumor types." (PMID 40813985, 2025). "Many TRPV1 modulators have also been evaluated as cancer therapies, given their effect on cancer cell proliferation through excessive Ca2+ influx, which is knowingly cytotoxic." (PMID 39940997, 2025). "Compound binding to these sites modulates TRPV1 sensitivity and function, we need to elucidate their ligand structures and corresponding TRPV1 sites, mechanisms of action in the cancer process, and final effects." (PMID 40007993, 2025). "TRPV1 has emerged as a potential target for cancer treatment due to its role in regulating tumor growth, cell apoptosis, and the tumor micro-environment." (PMID 40007993, 2025). "TRPV1 is expressed not only in cancer cells, but also in sensory neurons, the central nervous system, and a variety of immune cells (lymphocytes, dendritic cells, macrophages, and neutrophils)." (PMID 40007993, 2025). "Upon NIR irradiation, TRPV1 activation triggered a calcium influx that led cancer cells to apoptosis." (PMID 40813985, 2025).
cancer (continued). "TRPV1 expression has been examined in cancers of many organ sites and established cancer cell lines." (PMID 39779619, 2025). "TRPV1 is the subject of investigation in relation to two specific health conditions: cancer pain (NCT04572776) and gastrointestinal tumor inflammation (NCT02666976)." (PMID 40813985, 2025). "Collectively, the present results support a coherent mechanistic framework linking hypoxia, HIF-1α stabilization, and TRPV1-mediated Ca2+ dynamics, with direct implications for therapeutic targeting in estrogen-responsive cancers." (PMID 41303593, 2025). "There are many confusing cell culture studies of TRPV1 agonists as well as antagonists regarding cancer cell death and proliferation." (PMID 39779619, 2025). "Metabolites of cancer cells, such as lactic acid, induce local acidosis and activate ASICs/TRPV1 ion channels." (PMID 41132793, 2025). "Multiple Ca2+-handling proteins, including CACNA1D, CACNA2D1, TRPV4, TRPV1, TRPM4, MCU, and RyR1, exhibit cancer-associated overexpression or functional changes, correlating with poor prognosis and aggressive disease features." (PMID 41226294, 2025). "The expression level of TRPV1 also changed in the same cancer tissue, which was related to the grade of cancer tissue, pathological stage and tumor stage." (PMID 40007993, 2025). "Apparently the expression level of TRPV1 in each cancer cell line is highly heterogeneous, and the expression of TRPV1 is associated with different tumor micro-environments and different cancer-associated pathways." (PMID 40007993, 2025). "ROS-induced TRPV1-mediated Ca2+ has been shown to promote mitochondrial Ca2+ overload and caspase activation, thereby promoting apoptotic cell death in multiple cancer cell types." (PMID 40813985, 2025). "Pharmacological TRPV1 antagonists and genetic ablation approaches have demonstrated significant analgesic and anti-tumor effects in preclinical cancer models." (PMID 41009819, 2025). "The nanoplatform utilised the Fenton reaction to generate ̇OH, inducing CDT, while the PDA coating functioned as a pH- and NIR-sensitive gatekeeper, preventing premature drug release while allowing specific targeting of TRPV1 channels on cancer cells." (PMID 40813985, 2025). "Numerous studies have identified direct links between TRPV1 and cancer cell proliferation, apoptosis, and metastasis." (PMID 39273976, 2024). "For example, the regulation of heat shock transcription factor 1 (HSF1) by TRPV1 has been explored as a mechanism to amplify cancer thermo-immunotherapy, providing a novel approach to cancer treatment." (PMID 39407657, 2024). "Recent research focused on identifying compounds regulating the transient receptor potential vanilloid 1 (TRPV1) ion channel activity for the possibility of developing cancer therapeutics." (PMID 38791297, 2024). "Last, there are conflicting preclinical results regarding the effect of TRPV1 blockade on cancer progression that still baffle researchers." (PMID 38339399, 2024). "This review explores the analgesic potential of small molecule TRPV1 antagonists and the sensory afferent desensitization in cancer patients." (PMID 38339399, 2024). "TRPV1 is expressed in the sensory neurons of cancer patients experiencing pain, emphasizing its role in pain intensity modulation." (PMID 39407657, 2024). "The modulation of TRPV1 expression and function has been connected to changes in the tumor microenvironment and immune responses, with implications for cancer metastasis and patient prognosis." (PMID 39407657, 2024). "This innovative strategyrepresents a comprehensive approach to fine-tune the TME, significantlyamplifying the effectiveness of cancer immunotherapy by exploitingthe TRPV1 pathway and enabling in situ control ofimmunomodulation within the TME." (PMID 38344992, 2024). "There is good evidence both in preclinical and clinical studies that TRPV1-positive afferents play an important role in cancer pain." (PMID 38339399, 2024).
cancer (continued). "Experimental evidence showed that capsaicin can activate TRPV1 and showed potent anti-cancer activity against certain types of cancer both in Ca2+-dependent and -independent mechanisms." (PMID 38791297, 2024). "TRPV1, also known as the capsaicin receptor, is pivotal in cancer cell death and pain mediation, offering promise as a therapeutic target." (PMID 39407657, 2024). "In this review, we aim to explore the multifaceted roles of TRPV1 in cancer by its modulation mediated by capsaicin." (PMID 39407657, 2024). "More research is required to fully comprehend the potential of phytochemicals targeting TRPV1 in cancer treatment." (PMID 38791297, 2024). "Despite the potential of targeting the TRPV1-CGRP pathway for treating cancer pain and tumor growth, the development of TRPV1 blockers for clinical use has been hindered by side effects." (PMID 39407657, 2024). "TRPV1 activation through natural compounds like capsaicin presents a promising avenue for therapeutic intervention in cancer, for example, inhibiting tumor growth and metastasis through the induction of cell death pathways." (PMID 39407657, 2024). "Capsaicin’s interaction with TRPV1 channels induces apoptosis in various cancer types, disrupting cancer cell metabolism and inhibiting tumor growth." (PMID 39407657, 2024). "Capsaicin, the main bioactive pungent compound in chili peppers, interacts with TRPV1, leading to cellular calcium influx and depolarization, which is significant in the context of cancer due to cell-signaling-related cell growth and cell death." (PMID 39407657, 2024). "Capsaicin enhances the efficacy of 5-Fluorouracil (5-FU) in HT-29 cancer cells through increased oxidative stress and apoptosis due to TRPV1." (PMID 39407657, 2024). "By examining the alteration of TRPV1 in sensory neurons and its implications for cancer pain and chemosensitivity, we seek to provide insights into the complex interplay between cancer biology and sensory perception." (PMID 39407657, 2024). "Collectively, these studies underscore the multifaceted role of TRPV1 in cancer dynamics, offering insights into its dual function as both a tumor promoter and suppressor, depending on the context." (PMID 39407657, 2024). "Nanoparticle-mediated TRPV1 blockade can enhance the efficacy of cancer thermo-immunotherapy, proposing a novel approach for improving therapeutic outcomes." (PMID 39407657, 2024). "TRPV1 expression seems to contribute to gastric-mucosal inflammation and precursors of GC, which significantly increases in cancer precursor lesions but is completely lost in GC." (PMID 39125864, 2024). "Cancer-derived vesicles also evoke Ca2+ uptake in nociceptors, presumably by opening the TRPV1 channel." (PMID 38339399, 2024). "Taking these data together shows that the effect of TRPA1 and TRPV1 activation greatly depends on the cancer cell types and complex sensory–vascular–immune–tumor interactions in the cancer microenvironment." (PMID 38612571, 2024). "Several chemicals derived from plants have been found to interact with transient receptor potential vanilloid 1 (TRPV1) channels and exhibit antiproliferative activity in different cancer cell lines." (PMID 38791297, 2024). "Capsaicin-loaded nanoparticles selectively target cancer cells by activating TRPV1 channels, triggering calcium ion therapy within tumors." (PMID 39407657, 2024). "The calcium influx provoked by TRPV1 activation represents an opportunity to control cell proliferation, thereby significantly impacting cancer progression." (PMID 39407657, 2024). "Recent drug discovery studies revealed the TRPA1 and TRPV1 channels to be potential therapeutic targets in many diseases including asthma, pain, neuro-psychiatric disorders, and different types of cancers." (PMID 38612571, 2024). "Yet another important role of TRPV1 function in cancer growth and metastasis has also been documented; it can promote or suppress cancer cell death, depending on the type and environment." (PMID 38790047, 2024).
cancer (continued). "Recent findings have highlighted the significant roles of TRPV1 in cancer tumorigenesis and progression, as its expression levels are altered in various cancer cell types." (PMID 39273976, 2024). "Among emerging players in cancer biology, Transient Receptor Potential (TRP) channels, notably TRPV1, have garnered attention due to their altered expression in cancer cells and roles in tumorigenesis and progression." (PMID 39407657, 2024). "In preclinical studies, selective TRPV1 inactivation through genetic manipulation or pharmacological blockade was shown to ameliorate cancer pain." (PMID 38339399, 2024). "In this cancer-neuropathy model, the inhibition of TRPV1 and TRPV4 channel activity by their selective antagonists, capsazepine and HC-067047, respectively, transiently reversed the cancer-induced thermal and mechanical allodynia in a dose-dependent manner." (PMID 38730655, 2024). "One of the promising mechanisms for pain relief in cancer is the inhibition of TRPV1, mitigating these inflammatory responses." (PMID 39407657, 2024). "In this sense, capsaicin, a well-studied TRPV1 agonist, has shown efficacy in alleviating chronic cancer pain by desensitizing this channel, therefore influencing pain and reducing neuropeptide release from sensory neurons." (PMID 39407657, 2024). "In a murine cancer model (Lewis carcinoma inoculated into the paw), tumor growth was attenuated in both TRPV1-null and αCGRP-null mice compared to in wild-type littermates." (PMID 38339399, 2024). "For instance, nanoparticle-mediated TRPV1 channel blockade enhances cancer thermo-immunotherapy via HSF1 modulation." (PMID 39407657, 2024). "Taken together, these experiments imply the clinical value of selective TRPV1 blockade in patients with cancer pain." (PMID 38339399, 2024). "Studies show that overexpression of calcium-permeable ion channels, such as TRPV1, can trigger necrotic cell death in cancer cells." (PMID 39769488, 2024). "More research is required to clarify when TRPV1 blockade is suitable for treating cancer-related pain." (PMID 39407657, 2024). "The interplay between TRPV1 and key cancer molecular pathways, such as the Phosphoinositide 3-kinase/Protein kinase B (PI3K/AKT) and Mitogen-Activated Protein Kinase (MAPK) pathways, has been highlighted in several studies." (PMID 39407657, 2024). "In preclinical models of cancer pain, pharmacological blockade or the knock-down of TRPV1 also showed analgesic potential." (PMID 38339399, 2024). "TRPV1 activation by capsaicin also desensitizes pain pathways, offering relief to cancer patients suffering from chronic pain." (PMID 39407657, 2024). "There is preliminary evidence that cancer cells can synthesize substances capable of activating TRPV1." (PMID 38339399, 2024). "The TRPV1 channel is a significant player in cancer biology, primarily due to its ability to modulate downstream signaling pathways that are crucial for immune modulation, inflammation, and cell survival." (PMID 39407657, 2024). "In this review, we explore the current state of this field and compare the analgesic potential of TRPV1 antagonism and sensory afferent desensitization in cancer patients." (PMID 38339399, 2024). "Although many studies have already addressed the role of other TRP channels, including TRPA1 and TRPV1, in the process of cancer pain development, our review mainly focused on TRPV4’s action, addressing the uniqueness of this protein." (PMID 38730655, 2024). "The current review elucidates the comprehensive role of capsaicin in cancer therapy, particularly through the TRPV1 channel, highlighting its effects in various cells via different signaling pathways and discussing its limitations." (PMID 39407657, 2024). "A further layer of complexity to the Ca2+-dependent regulation of cancer hallmarks is added by the evidence that the same TRP isoform, e.g., TRP Vanilloid 1 (TRPV1), can exert opposing effects in different cancer types." (PMID 37393347, 2023).